ATF5 (activating transcription factor 5)
Diseases named in the same sentence as ATF5 in open-access papers (continued):
Sharing a sentence is not in itself a finding about the gene and the disease.
glioma (continued). "IE86 staining positively correlates with the staining of activating transcription factor 5 (ATF5) which is essential for glioma cell viability and proliferation suggesting that HCMV IE86 could have important implications in glioma biology." (PMID 28473657, 2017). "ATF5 expression was also shown to be upregulated in GBMs and anaplastic gliomas relative to low grade gliomas and normal cortical tissue, indicating that ATF5 expression may be associated with more malignant glioma phenotypes." (PMID 29137451, 2017). "Also shown in parallel with glioma, ATF5 activated expression of the early growth response factor 1 (EGR-1) gene in a breast cancer cell line via a novel ATF5 DNA regulatory element." (PMID 29137451, 2017). "Next, we examined ATF5 expression in various kinds of the glioma specimens." (PMID 28473657, 2017). "In vitro Pen-d/n-ATF5-RP entered into glioma cells and triggered massive apoptosis." (PMID 26863637, 2016). "Expression of d/n-ATF5 caused complete regression/eradication of gliomas induced from endogenous progenitor cells and did so without damage to normal brain tissue." (PMID 26863637, 2016). "Finally, Pen-d/n-ATF5 is able to promote apoptosis in glioma stem cell lines or so-called “tumor-initiating cells”." (PMID 26863637, 2016). "In addition, the present study found that HCMV infection regulates the expression of ATF5 in glioma." (PMID 25120656, 2014). "ATF5 loss of function induces apoptosis in a number of glioma and breast cancer cell lines, however, interfering with ATF5 function in non-tumor brain cells has not been found to affect their survival." (PMID 25120656, 2014). "Furthermore, previous studies have shown that Bcl-2 is a downstream target of ATF5 that mediates the pro-survival function of ATF5 in C6 glioma and MCF-7 breast cancer cells." (PMID 25120656, 2014). "Because of ATF5’s role as a critical transcription factor involved in cellular growth and apoptosis, this may explain, in part, the slower growth phenotype of IDH1mut gliomas." (PMID 38445960, 2024). "In addition, GlioVis analysis of TCGA RNA-seq data showed that ATF5 expression was decreased over 2-fold in the IDH1mut (n = 429) glioma patient cohort when compared with the IDH1wt (n = 233) cohort in a pairwise t test (P < 6.6E-65, with Bonferroni multiple testing correction)." (PMID 38445960, 2024). "Moreover, consistent with interference with CEBPB, CEPBD and ATF5 activities, in T98G and other non-glioma cancer lines, Dpep and Bpep suppressed expression of direct CEBPB/CEBPD targets IL6 and IL8 and of direct ATF5 and CEBPB target asparagine synthetase (ASNS)." (PMID 36831248, 2023). "Moreover, ATF5 acetylation at K29 in a P300-dependent manner by immediate-early 2 gene product (IE86) human cytomegalovirus (HCMV) (86 kDa immediate-early protein) is known to promote glioma cell survival." (PMID 35806136, 2022). "Interestingly, ATF5 expression is colocalized and correlated with HCMV IE expression, indicating that ATF5 may play a crucial role in the malignant phenotype of gliomas increasing under HCMV infection." (PMID 28473657, 2017). "In addition, ATF5 induction in glioma cells enhances drug resistance." (PMID 25682872, 2015). "In glioma, CREB3L2 activates the transcription factor Activating Transcription Factor 5 (ATF5) by binding to its promoter region." (PMID 41301006, 2025). "As we have reviewed thus far, there is abundant evidence to support targeting of ATF5, CEBPB and CEBPD individually for therapeutic treatment of gliomas and an array of other cancer types." (PMID 36831248, 2023). "In conclusion, our study confirms the existence of HCMV in gliomas and illustrates an ATF5-mediated central role of IE protein regulating glioma cells proliferation and survival in HCMV infected U87 glioma cells." (PMID 28473657, 2017). "ATF5 and IE86 expression positively correlates with the degree of malignancy in gliomas (#F = 50.87, P < 0.05; *F = 482.24, P < 0.05)." (PMID 28473657, 2017).
glioma (continued). "Our findings confirm the existence of HCMV infection and ATF5 expression in gliomas and reveal an essential role of HCMV IE protein in posttranslational regulation of ATF5 that mediates the unique function of IE in promoting glioma cell survival." (PMID 28473657, 2017). "Activating transcription factor 5 (ATF5; activating transcription factor/CREB family member) is a potential target for treatment of gliomas." (PMID 26863637, 2016). "It is additionally relevant that ATF5 is also expressed by neural and glial progenitor cells, CD133+ glioma stem cells, and by stem cells isolated from human glioblastomas." (PMID 26863637, 2016). "Further studies have shown that m6A-mediated downregulation of activating transcription factor 5 (ATF5) mRNA may also play an important role in regulating proliferation and apoptosis in IDH mutant glioma." (PMID 39596840, 2024). "We also show how this IDH1mut → D-2-HG ⊣ FTO axis may inhibit tumor growth through downregulation of activating transcription factor 5 (ATF5) mRNA, a transcription factor involved in proliferation and apoptosis in glioma." (PMID 38445960, 2024). "Further studies should explore whether ATF5/FOSL2 and GNAL compete or inhibit each other upstream or downstream during the development of glioma." (PMID 38686055, 2024). "For all glioma types taken together (163 GBM and 518 low-grade gliomas), there was a highly significant increase in mean survival time for those with low-expression ATF5 tumors." (PMID 36831248, 2023). "A related question that has not been well studied is the expression of ATF5 in brain tumors other than gliomas." (PMID 36831248, 2023). "In the tumorigenesis and migration pathways, ATF5 transcription can be activated by the tumor cell growth and migration promoter E74-like E26 transforming sequence (ETS) transcription factor (ELF1), increasing the malignancy of gliomas." (PMID 35806136, 2022). "Our previous work have confirmed that ATF5 is highly expressed in glioma cells but not in normal brain tissues." (PMID 28473657, 2017). "ATF5 expression is colocalized and correlated with HCMV IE expression in glioma tissues." (PMID 28473657, 2017). "Our study investigated ATF5-mediated survival mechanism which is essential in malignant glioma genesis is posttranslational regulated by HCMV and revealed a new important mechanism that how does the HCMV infection enhance cancer cell survival in glioma." (PMID 28473657, 2017). "Disturbance on ATF5 function or expression drives apoptosis of glioma cell lines while not affecting survival of nonneoplastic brain cells." (PMID 28473657, 2017). "ATF5, a member of the ATF/CREB family of basic leucine zipper proteins, is an anti-apoptotic protein, which is highly expressed in malignant glioma, but not in normal brain tissues, and is essential for the survival of glioma cells." (PMID 25120656, 2014). "Activating transcription factor 5 (ATF5) is an anti-apoptotic protein that is highly expressed in malignant glioma but not normal brain tissues, and is essential for glioma cell survival." (PMID 21311102, 2010). "The intriguing evidence that ATF5 exerts prosurvival effects in glioma and not in healthy brain tissue led us to consider whether ATF5 downregulation, mediated by m6A enrichment of ATF5 transcripts, might serve as a downstream effector of reduced tumor growth." (PMID 38445960, 2024). "Several reports show that ATF5 mediates the survival of breast cancer, glioma, and transformed myeloid cells but is not required for the survival of non-transformed astrocytes, fibroblasts, and breast epithelial cells, thus enabling specificity of ATF5 clinical targeting." (PMID 28785242, 2017). "Among additional targets is activating transcription factor 5 (ATF5), an anti-apoptotic protein that is highly expressed in malignant glioma but not normal brain tissues, and is essential for glioma cell survival." (PMID 22228887, 2011).
glioblastoma (21 papers, 2010 to 2025). The most malignant astrocytic tumor (WHO grade IV). "Likewise, given that ATF5 is aberrantly over-expressed in many tumor types, it would be interesting to investigate whether high ATF5 expression is generally linked to poor prognosis of cancer patients, as has been observed in glioblastoma and CLL." (PMID 21311102, 2010). "As an anti-apoptotic protein, ATF5 is highly expressed in neuroblastoma, medulloblastoma, and glioblastoma, it promotes cancer cell survival." (PMID 38686055, 2024). "In both a rat C6 model and a patient-derived glioblastoma-initiating cell xenograft model in mice, ATF5-CaP-rHDL promoted apoptotic death of the implanted tumor cells and significantly extended animal survival." (PMID 36831248, 2023). "ATF5, a key UPRmt regulator in mammals, has been observed to be upregulated in glioblastoma, breast, pancreas, rectal, and ovarian cancers." (PMID 36768800, 2023). "ATF5 is upregulated in glioblastoma as well as cancers of the breast, pancreas, rectum, and ovaries." (PMID 35864539, 2022). "In glioblastoma, non-small cell lung cancer, and pancreatic cancer, ATF5 regulates the protein expression of deubiquitinase USP9X, which, in turn, stabilizes B cell lymphoma 2 (BCL-2) and myeloid leukemia 1 (MCL1)." (PMID 35864539, 2022). "To further assess effects of dn-ATF5 on survivin expression and localization at the cellular level, we transfected T98G and LN229 glioblastoma cells with a GFP-FLAG-dn-ATF5 construct or with a control plasmid expressing only GFP." (PMID 31551409, 2019). "After that, theanti-glioblastoma activity of ATF5 siRNA-loaded CaP-rHDL (ATF5-CaP-rHDL) was evaluatedboth in vitro and in vivo." (PMID 28489075, 2017). "ATF5-CaP-rHDLwas found to dramatically reduce the expression of ATF5 mRNA and protein andefficiently induce apoptosis in glioblastoma cells." (PMID 28489075, 2017). "In mice modelraised by C6 glioblastoma cells, ATF5-CaP-rHDL, ATF5-CaP-LNC and NC-CaP-rHDLwere given intravenously (i.v.)at the siRNA dose of0.36 mg kg−1 on day 6, 8, 10 and 12 aftersurgery." (PMID 28489075, 2017). "Contrary to the oncogenic role of ATF5 in glioblastoma and other previously discussed malignancies, ATF5 appears to elicit a tumor suppressive role in hepatocellular carcinomas (HCCs)." (PMID 29137451, 2017). "Initial expression profiling of glioblastoma (GBM) revealed ATF5 expression was inversely correlated with overall patient survival, indicating the importance of ATF5 expression to patient outcomes in the clinic." (PMID 29137451, 2017). "These actions are similar to what others and we have previously reported for multiple rodent and human glioblastoma cell lines transfected with d/n-ATF5 constructs or exposed to ATF5 siRNA." (PMID 26863637, 2016). "Transfection of this deleted construct into C6 glioblastoma cells showed equal effectiveness as the full length d/n-ATF5 in promoting apoptosis (p < 0.05)." (PMID 26863637, 2016). "When added to serum-containing cultures of rat C6 and human U87 glioblastoma cells, both Pen-control-RP and Pen-d/n-ATF5-RP were readily detectable in the cells within 2-4 h and remained detectable for at least 24 h." (PMID 26863637, 2016). "ATF5 is highly expressed in human glioblastomas with expression levels reported to inversely correlate with disease prognosis." (PMID 26863637, 2016). "The present study showed that HCMV infection suppressed apoptosis in glioblastoma U87 cells by regulating the expression of ATF5." (PMID 25120656, 2014). "The present study revealed that HCMV infection blocks apoptosis in glioblastoma U87 cells and increases the expression levels of the ATF5 and Bcl-2 to BAX ratio." (PMID 25120656, 2014). "Studies have shown that anti-apoptotic Bcl-2 is regulated by ATF5 in glioblastoma cells and BAX is an apoptosis member of the Bcl-2 family." (PMID 25120656, 2014).
glioblastoma (continued). "In one study, a retrospective analysis of 23 individuals with glioblastoma revealed that patients harboring tumors expressing high levels of ATF5 had substantially shorter survival times than those with tumors in which ATF5 expression was low or undetectable." (PMID 21311102, 2010). "ATF5 knockdown promotes apoptosis in glioblastoma and breast cancer cells." (PMID 38014922, 2023). "ATF5 also acts as a prosurvival factor that supports cellular adaptation to stress and is highly expressed in multiple malignancies, including glioblastoma, breast cancer, colon cancer, and osteosarcoma." (PMID 38014922, 2023). "Furthermore, HCMV infection suppressed the apoptosis of glioblastoma cells by increasing the expression level of activating transcription factor 5 (ATF5) and the B cell lymphoma/leukemia-2 (Bcl-2)-to-Bcl-2-associated X (BAX) protein ratio." (PMID 33921122, 2021). "Similar results were achieved by transfecting T98G glioblastoma cells with 3xFLAG-dn-ATF5." (PMID 31551409, 2019). "By utilizing this uniqueendocytosis pathway, here we create a biologically inspired nanostructure that caninduce cancer cells to ‘drink drugs' for targeting activatingtranscription factor-5 (ATF5), an overexpressed anti-apoptotic transcription factorin glioblastoma." (PMID 28489075, 2017). "The basis for the role of ATF5 in survival of tumor cells is not completely understood, but mechanistic studies have suggested that ATF5 supports glioblastoma cell survival by regulating expression of the anti-apoptotic proteins MCL1 and Bcl2 and of the Egr-1 gene." (PMID 26863637, 2016). "Furthermore, in glioblastoma U87 cells, HCMV infection induced cellular proliferation in parallel with an increase in the expression level of ATF5 and B-cell lymphoma/leukemia-2 to Bcl-2-associated X protein ratio." (PMID 25120656, 2014). "Further investigations will reveal whether the ATF5-mediated survival pathway represents an efficacious target for the treatment of cancers in addition to glioblastoma." (PMID 21311102, 2010). "Notably, increased levels of ATF5 have been observed in primary brain tumors, and ATF5 expression is particularly high in glioblastoma, an aggressive form of malignant glioma." (PMID 21311102, 2010). "In addition, ATF5 regulates B cell lymphoma-extra large (Bcl-xL) expression in glioblastoma cells." (PMID 35864539, 2022). "In addition to glioblastoma, ATF5 is also essential for the viability of other cancer cell types." (PMID 21311102, 2010). "Instead, among their few marker genes was ATF5, which plays a neuroprotective role during endoplasmic reticulum stress, and XIST, which is upregulated across a wide range of cancers, including glioblastoma." (PMID 38848215, 2024). "ATF5 can also activate another anti-apoptotic gene, B cell leukemia/lymphoma 2 (BCL2) transcription, therefore, increasing glioblastoma and breast cancer survival." (PMID 35806136, 2022). "Consistent with theapoptotic results, in C6 glioblastoma animal, survival in Kaplan–Meiersurvival curve showed that on day 26, the survival rate of the saline,NC-CaP-rHDL, ATF5-CaP-LNC and ATF5-CaP-rHDL-treated animals was 0, 11, 48 and100%, respectively." (PMID 28489075, 2017). "ATF5 is highly expressed in primary brain tumors, especially in glioblastoma, and plays a key role in promoting cancer cell survival through the CREB3L2/ATF5/MCL1 pathway." (PMID 27023521, 2016). "Recent studies have characterized the oncogenic role of ATF5 in the development of several different types of cancer, notably glioblastoma." (PMID 29137451, 2017). "Inhibition of ATF5 activity, using RNAi or a dominant negative form of ATF5, kills human and rat glioblastoma cells but does not affect normal cells surrounding the tumor, indicating ATF5 is selectively essential for the survival of glioblastoma cells." (PMID 28473657, 2017).
glioblastoma (continued). "Preclinical assessment of a systemically deliverable dominant-negative ATF5 (dnATF5) biologic has found that targeting ATF5 results in tumor regression and tumor growth inhibition of glioblastoma xenografts in mouse models." (PMID 29137451, 2017). "Interference with ATF5 function by a dominant negative-form of the protein promotes massive apoptosis of glioblastoma cells in vitro and in vivo without detrimental effect on normal cells." (PMID 26863637, 2016). "Due to the high prevalence of HCMV and ATF5 expression observed in vivo in human malignant glioma, the aim of the present study was to investigate the role of the ATF5 signaling pathway in HCMV-infected glioblastoma cells." (PMID 25120656, 2014). "Inhibition of ATF5 activity, using a dominant negative form of ATF5, kills human and rat glioblastoma cells but does not affect normal cells surrounding the tumor, indicating ATF5 is selectively essential for the survival of glioblastoma cells." (PMID 21311102, 2010). "Therefore, the effect of ATF5 knockdown can be highly cell type-dependent and could therefore explain why BCL2 seems to be regulated by ATF5 in some glioblastoma cell lines but not in others." (PMID 29137451, 2017).